RNU6-533P (RNA, U6 small nuclear 533, pseudogene)
Gene: Small nuclear RNA gene on chromosome 8 (36,309,584 to 36,309,690, reverse strand). Ensembl gene ENSG00000206871.
Homologues: Orthologues: chimpanzee U6 (99% identical), pig U6 (85% identical), rat U6 (85% identical). Paralogues in human: RNU6-38P (90% identical), RNU6-1145P (88% identical), RNU6-25P (87% identical), RNU6-29P (87% identical), RNU6-41P (87% identical), RNU6-74P (87% identical), RNU6-1 (86% identical), RNU6-1331P (86% identical), RNU6-15P (86% identical), RNU6-2 (86% identical), RNU6-20P (86% identical), RNU6-30P (86% identical), and 1286 more.